MIR744 (microRNA 744)
Synonyms: hsa-mir-744; MIRN744; mir-744
Gene: MicroRNA gene on chromosome 17 (12,081,899 to 12,081,996, forward strand). Ensembl gene ENSG00000266297.
Gene Ontology:
Biological process: miRNA-mediated post-transcriptional gene silencing
Cellular component: RISC complex
Homologues: Orthologues: chimpanzee ptr-mir-744 (100% identical), macaque MIR744 (100% identical), guinea pig MIR744 (98% identical), rabbit MIR744 (98% identical), mouse Mir744 (97% identical), dog MIR744 (95% identical), pig ssc-mir-744 (81% identical).